ATF6 (activating transcription factor 6)
Diseases named in the same sentence as ATF6 in open-access papers (continued):
Sharing a sentence is not in itself a finding about the gene and the disease.
brain injury (2 papers, 2023). Acute and chronic (see also brain INJURIES, CHRONIC) injuries to the brain, including the cerebral hemispheres, CEREBELLUM, and brain STEM. "Similar to previous studies, we demonstrated that ATF6, Bip, CHOP, IRE1, PERK, and Caspase-3 were upregulated after ischemic brain injury." (PMID 36812289, 2023).
chondrodysplasia (2 papers, 2022 to 2023). "In Schmid metaphyseal chondrodysplasia, ER stress occurs in chondrocytes and activates the PERK, ATF6, and IRE1 pathways, whereas IRE1 is not involved in the short-bone-length phenotype." (PMID 37746069, 2023).
chronic kidney disease (2 papers, 2025). Impairment of the renal function secondary to chronic kidney damage persisting for three or more months. "In context, Sig-1R agonist PRE-084 ameliorated kidney injury in rat model of adenine-induced chronic kidney disease by decreasing the expression of ER stress proteins; PERK, ATF-6, and IRE-1α as well as reducing caspase-12." (PMID 40711497, 2025).
colon adenoma (2 papers, 2022 to 2025). An adenoma that arises from the colon. "Most relevant to our mouse model and the role of ATF6 signalling in colon adenoma development in tg/tg mice is the SPF UP cluster." (PMID 40890536, 2025). "Mice with intestinal epithelial expression of the active form of ATF6 developed spontaneous colon adenomas at 12 weeks of age, and in CRC patients increased ATF6 expression was associated with reduced time of disease-free survival." (PMID 36300096, 2022).
COVID-19 (2 papers, 2022 to 2024). A disease caused by infection with severe acute respiratory syndrome coronavirus 2. "UPR modulators of ATF6, IRE1 and PERK pathways have been evaluated as potential therapeutic targets against COVID-19, reducing the viral load and alleviating the associated pathophysiology." (PMID 38247815, 2024).
cytomegalovirus infection (2 papers, 2020 to 2021). A herpesvirus infection caused by Cytomegalovirus. "Similarly, the productive HCMV infection also triggers ER stress, but selectively induces PERK and IRE1 pathways, but not ATF6 pathway." (PMID 33919712, 2021).
deafness (2 papers, 2025). An inherited or acquired condition characterized by the complete loss of the ability to hear from one or both ears. "Thus, seeing that the patients present with both blindness and deafness, individuals with ATF6 mutations can now be classified under the syndromic hearing loss category." (PMID 39895634, 2025).
dementia (2 papers, 2022 to 2023). Loss of intellectual abilities interfering with an individual's social and occupational functions. "These assumptions agree with our molecular data showing increased PERK, XBP1, and CHOP expression levels in MCI patients and enhanced ATF6 and BAX in DAT patients, suggesting a pronounced RER stress at the onset of dementia, potentially followed by apoptosis at later stages of the disease." (PMID 37175616, 2023).
Depression (2 papers, 2015 to 2025). "The correlations between biomarker levels (IL-18, IRE1, pERK, ATF6) and CECS scores (Anger, Depression, Anxiety subscales, and total score) reveal distinct patterns influenced by the presence and duration of PTSD, providing insights into the neurobiological and emotional dynamics of the disorder." (PMID 40806635, 2025).
fibrosarcoma (2 papers, 2014 to 2024). A malignant mesenchymal fibroblastic neoplasm affecting the soft tissue and bone. "For instance, tumor necrosis factor-alpha (TNF-α) causes ER stress, activating PERK, IRE1 α, and ATF6 in fibrosarcoma cells." (PMID 39451231, 2024). "In A549 cells, nuclear-localized ATF6 was observed; however, no activating events can be detected in human fibrosarcoma 2fTGH cells, therefore, GPR78 upregulation may be mediated in an ATF6-independent fashion." (PMID 25140166, 2014).
hearing loss (2 papers, 2025). "Notably, the authors now report that patients carrying the c.970C > T ATF6 variant also have hearing loss." (PMID 39895634, 2025).
hyperthyroidism (2 papers, 2021 to 2022). Overactivity of the thyroid gland resulting in overproduction of thyroid hormone and increased metabolic rate. "In our study, we think that 12 mg/L thyroxine-induced hyperthyroidism causes ER stress in kidney tissue, and the damage caused by hyperthyroidism in kidney tissue is associated with regulation of especially ATF6 and PERK." (PMID 33754657, 2021). "Hyperthyroidism caused an increase in expression of GRP78 (2.16 fold), ATF6 (2.82 fold), PERK (1.95 fold), IRE1 (1.60 fold), and TRPC1 (1.53 fold) when compared to the control group." (PMID 33754657, 2021).
insulinoma (2 papers, 2021 to 2022). "It has been reported that knockdown of WFS1 induced upregulation of ATF6α and its target genes in the rat insulinoma cells." (PMID 36527091, 2022).
lipid metabolism disorder (2 papers, 2021 to 2025). "Moreover, CACE can alleviate lipid metabolism disorder through inhibiting ER stress via PERK and ATF6 signaling pathways and activating PPARs with upregulating PPARα expression and downregulating PPARγ expression." (PMID 33688365, 2021).
liver fibrosis (2 papers, 2017 to 2023). "This included genes associated with metabolism (Fabp1, Insr), genes associated with cell stress (Atf6, Ddit3, and Eif2ak3), genes associated with liver fibrosis (Hgf, Sp1, and Timp1) and genes associated with the inflammatory response (Tnf, Ptpn22, and Pparg)." (PMID 28686204, 2017).
lung adenocarcinoma (2 papers, 2021 to 2022). A carcinoma that arises from the lung and is characterized by the presence of malignant glandular epithelial cells. "Consistently, an examination of a public mRNA database showed that the levels of ATF6 mRNA were elevated in CAFs from patients with lung adenocarcinomas, compared to normal fibroblasts." (PMID 33670717, 2021). "In both lung adenocarcinoma (AD) and lung squamous carcer (SC), the tumors expressed much higher levels of ATF6B relative to ATF6." (PMID 35625704, 2022).
multiple sclerosis (2 papers, 2022 to 2025). A progressive autoimmune disorder affecting the central nervous system resulting in demyelination. "Interestingly, the loss of ATF6 has some beneficial effects: Atf6–/– mice resist paralysis and show reduced spinal cord inflammation in a model of multiple sclerosis." (PMID 39570676, 2025). "UPR can affect Multiple Sclerosis (MS) and several neurological and metabolic diseases via the BiP stress sensor, resulting in ATF6, PERK and IRE1 activation." (PMID 35806376, 2022).
oral cancer (2 papers, 2019 to 2023). "The relative mRNA expression of these ER-stress-associated genes (BIP, PERK, IRE1α, and ATF6) in oral cancer cells was generally higher than in the control, while it showed no change in normal cells." (PMID 36835397, 2023). "The mRNA expressions for ER stress signaling, including BIP, PERK, IRE1α, and ATF6, were assessed for manoalide treatment for 24 h in oral cancer cells and normal cells." (PMID 36835397, 2023). "Generally, manoalide differentially influences higher mRNA and protein expressions of ER-stress-associated genes (PERK, IRE1α, ATF6, and BIP) in oral cancer cells than in normal cells." (PMID 36835397, 2023). "IRE1α and ATF6 genes were overexpressed in oral cancer (Ca9-22) cells at 5 and 10 μM of manoalide." (PMID 36835397, 2023). "BIP, IRE1α, and ATF6 genes were upregulated in oral cancer (CAL 27) cells at a high dose (10 μM)." (PMID 36835397, 2023). "Similarly, the protein expressions of BIP, PERK, IRE1α, and ATF6 genes of oral cancer cells and normal cells showed a similar tendency in their mRNA expressions." (PMID 36835397, 2023). "Moreover, silencing of VCP (XBP1s and ATF6α target) or calreticulin (ATF6α target) resulted in reduced proliferation rate and decreased anchorage-independent growth in soft agar in oral cancer cells." (PMID 31151143, 2019).
osteoarthritis (2 papers, 2016 to 2022). A noninflammatory degenerative joint disease occurring chiefly in older persons, characterized by degeneration of the articular cartilage, hypertrophy of bone at the margins and changes in the synovial membrane. "When compared to FLSs from patients with osteoarthritis (n=9), the expression of ATF6α in RA FLSs (n=9) was markedly increased, both at mRNA and protein levels." (PMID 36300114, 2022).
pancreatitis (2 papers, 2020 to 2024). Inflammation of the pancreas. "Irisin addition up-regulated the expression of pro-survival UPR markers (ATF6 and XBP-1) and reduced UPR pro-apoptotic markers (CHOP) under cer-pancreatitis and induced ER stress (tunicamycin), consequently increasing cells viability." (PMID 38927047, 2024). "Pancreatitis induction (cerulein (cer)) resulted in a significant up-regulation of the PPARγ-PGC1α-FNDC5 axis, PL expression and secretion and endoplasmic reticulum (ER) stress unfolded protein response (UPR) signal-transduction markers (CHOP, XBP-1 and ATF6)." (PMID 38927047, 2024). "Similarly, cer-pancreatitis induction significantly up-regulated the CHOP levels by 7.3-fold (transcript) and by 2-fold (protein), XBP-1 levels by 3.2-fold (transcript) and by 9.7-fold (protein) and Atf6 by 1.6-fold (transcript) compared to the control." (PMID 38927047, 2024).
prediabetes (2 papers, 2020 to 2021). "Interestingly, it has also been found that genetic variation in ATF6 is associated with prediabetes in the Chinese Han population." (PMID 32724824, 2020). "Specially, literatures have indicated that the genetic variation in ATF6 is related to prediabetes in the Chinese Han population." (PMID 35140684, 2021).
protein misfolding diseases (2 papers, 2016 to 2026). "The potential to improve ER quality control in protein misfolding diseases through activation of ATF6 led to a significant interest in developing pharmacologic approaches that selectively induce activation of this UPR transcriptional program." (PMID 41586813, 2026).
pulmonary arterial hypertension (2 papers, 2021 to 2023). Pulmonary arterial hypertension (PAH) is a group of diseases characterized by mean pulmonary artery pressure >20 mmHg and elevated pulmonary arterial resistance leading to right heart failure. "In the chronic hypoxic mouse pulmonary hypertension model, all UPR pathways are activated, and the expressions of ATF6, PERK, IRE1α, and CHOP increase, indicating that ERS is involved in the occurrence and development of pulmonary hypertension." (PMID 37103050, 2023).
retinitis pigmentosa (2 papers, 2023). Retinitis pigmentosa (RP) is an inherited retinal dystrophy leading to progressive loss of the photoreceptors and retinal pigment epithelium and resulting in blindness usually after several decades. "A series of studies solidified the critical role of basal activity of ubiquitously expressed activating transcription factor 6 (ATF6) in regulating stress responses of rods in retinitis pigmentosa and the preservation of cones in humans." (PMID 37450596, 2023).
rheumatoid arthritis (2 papers, 2022 to 2024). A chronic, systemic autoimmune disorder characterized by inflammation in the synovial membranes and articular surfaces. "The contribution of activating transcription factor 6α (ATF6α) in rheumatoid arthritis (RA) pathogenesis, especially on fibroblast-like synoviocytes (FLSs), has been suggested by its sensitivity to inflammatory stimulus." (PMID 36300114, 2022).
Rotavirus infection (2 papers, 2011 to 2013). Infection with any of the rotaviruses. "Therefore, inhibition of ATF6α might be an effective therapeutic target against rotavirus infection." (PMID 23716639, 2013).
Salmonella Infections (2 papers, 2021 to 2025). Infections with bacteria of the genus SALMONELLA. "However, we did not observe any increase in XBP1 recruitment inside the nucleus upon infection at any time point post-infection, suggesting that Salmonella infection upregulates UPR by PERK and ATF6 pathways in HeLa cells." (PMID 40272166, 2025). "Of note, knockdown of ATF6 or PERK did not affect E2F1 downregulation elicited by Salmonella infection or secretome treatment, indicating that neither of these branches contributes to E2F1 regulation in these biological settings." (PMID 34099666, 2021). "Of note, Salmonella infection or treatment with the secretome of Salmonella-infected cells did not activate the two additional ER-stress sensors—ATF6 and PERK." (PMID 34099666, 2021). "Mechanistically, we show that Salmonella infection and treatment with secretome of infected cells specifically activates the ER-stress sensor IRE1, whereas the two other ER-stress response branches mediated by ATF6 and PERK are not activated." (PMID 34099666, 2021).
schizophrenia (2 papers, 2023 to 2025). A major psychotic disorder characterized by abnormalities in the perception or expression of reality. "The three major UPR pathways are directly or indirectly linked to ATF6, with XBP1, a risk factor for schizophrenia, being a downstream target gene of ATF6." (PMID 37376599, 2023). "Our bioinformatic analysis of mRNA samples from the prefrontal cortex of schizophrenic patients and healthy controls indicated an increased level of ATF6 in schizophrenia." (PMID 37376599, 2023). "ATF6B and ATF6, which are activated by the inactive cyclic AMP-dependent transcription factor ATF6 during ER stress, were found to be the predominant DEGs and shared genes between schizophrenia DEGs and ER stress-related genes." (PMID 37376599, 2023). "Our correlation analysis results revealed a positive correlation between ERVW-1 and ATF6 in patients with recent-onset schizophrenia." (PMID 37376599, 2023). "In this study, we reported an increase in ATF6 expression in schizophrenia and its correlation with ERVW-1." (PMID 37376599, 2023). "In summary, the bioinformatic analysis provided evidence that ATF6 could serve as a biomarker for the early detection of schizophrenia." (PMID 37376599, 2023). "Our results suggest that ERVW-1 might participate in schizophrenia by upregulating ATF6." (PMID 37376599, 2023). "In summary, there was aberrant expression of ATF6, XBP1, and GANAB in the serum of schizophrenic patients, and these proteins displayed significant correlations with ERVW-1 in schizophrenia." (PMID 37376599, 2023). "In conclusion, GANAB participates in the ERVW-1-induced ATF6-mediated UPR pathway, leading to ER stress and contributing to the pathogenesis of schizophrenia." (PMID 37376599, 2023). "In conclusion, ERVW-1 induced ER stress by suppressing GANAB expression, thereby upregulating the expression of ATF6 and XBP1 and ultimately contributing to the development of schizophrenia." (PMID 37376599, 2023). "Taken together, ATF6, BCL-2, and ERVW-1 displayed a significant correlation with XBP1 in schizophrenia." (PMID 37376599, 2023). "Subsequent research indicated that the UPR gene called XBP1 had a positive correlation with ATF6, BCL-2, and ERVW-1 in individuals with schizophrenia using Spearman correlation analysis." (PMID 37376599, 2023). "These molecular signatures suggest that ATF6 and XBP1 may serve as biomarkers and functional contributors to schizophrenia." (PMID 41473415, 2025). "Furthermore, we visualized the multiple correlations and regression analyses among ERVW-1, GANAB, ATF6, and XBP1 in the serum of individuals with recent-onset schizophrenia (n = 39) using a heatmap." (PMID 37376599, 2023). "Interestingly, in GSE21138, ERVW-1 exhibited a significant positive correlation with XBP1 at the transcriptional level in the prefrontal cortex of individuals with schizophrenia, suggesting a connection among ERVW-1, ATF6, and XBP1." (PMID 37376599, 2023). "In this paper, we found that ATF6 and XBP1 could be potential serum biomarkers of schizophrenia." (PMID 37376599, 2023). "Therefore, we propose that ATF6, XBP1, and GANAB might serve as potential serum biomarkers of schizophrenia." (PMID 37376599, 2023). "However, the relationship among GANAB, ATF6, and schizophrenia has not been reported, and there is insufficient evidence to establish a correlation between UPR and schizophrenia." (PMID 37376599, 2023). "Interestingly, previous studies have reported that ATF6 induces XBP1 mRNA, which aligns with our findings of a positive correlation between ATF6 and XBP1 in the bioinformatic analysis and correlation analysis in schizophrenia." (PMID 37376599, 2023). "ATF6 and ATF6B are homologs, so it is not surprising that the ATF6 mRNA level was also increased by 1.3 times in individuals with schizophrenia compared with healthy controls." (PMID 37376599, 2023).
subarachnoid hemorrhage (2 papers, 2019 to 2023). A serious neurological disorder characterized by intracranial hemorrhage into the subarachnoid space. "Apelin-13 can ameliorate neurological function after subarachnoid hemorrhage due to the inhibition of ATF6, which reduced ER stress-induced apoptosis and blood–brain barrier disruption." (PMID 36769462, 2023).
acute myeloid leukemia (1 paper, 2024). Acute myeloid leukemia (AML) is a group of neoplasms arising from precursor cells committed to the myeloid cell-line differentiation. "Previous studies have pointed out that ASP can up-regulate the expression of ATF6 in acute myeloid leukemia cells U937 and HL-60, activate ER stress, and induce apoptosis." (PMID 38896161, 2024).
airway hyperresponsiveness (1 paper, 2013). "However, the role of ATF6α and ERp57 in regulating airway hyperresponsiveness is unknown at this point." (PMID 24364984, 2013).
allergic reactions (1 paper, 2022). "In our cell model, treatment with HDM also increases the expression of UPR, including the ATF6, CHOP, and IRE1 genes, which are critical in allergic reactions and in asthmatic patients." (PMID 35057008, 2022).
Alport syndrome (1 paper, 2020). A rare renal disease characterized by glomerular nephropathy with hematuria progressing to end-stage renal disease (ESRD), frequently associated with sensorineural deafness, and occasionally with ocular anomalies. "We tested for protein expression of the ERS markers Bip, ATF6, IRE1α, and PERK, as well as their active forms in the WT and Alport syndrome-specific iPSCs." (PMID 32117450, 2020). "Therefore, we tested ATF6, IRE1α, and PERK, as well as their active forms, p50-ATF6, p-IRE1α, and p-PEKR, in WT and Alport syndrome fibroblasts." (PMID 32117450, 2020).
aortic aneurysm (1 paper, 2023). A ruptured aneurysm located in the wall of the proximal portion of the descending aorta proceeding from the arch of the aorta. "Taken together, the results have demonstrated that three ER stress pathways, ATF6, PERK, and IRE1, participate in the pathogenesis of human aortic aneurysms and mouse Ang II abdominal aortic and thoracic aneurysms." (PMID 37731512, 2023).
artery occlusion (1 paper, 2024). "After coronary artery occlusion (CAO), sFRP2transgenic mice exhibited smaller infarct sizes owing to increased angiogenesis,which was mediated by activating transcription factor 6 (ATF6) and connectivetissue growth factor (CTGF)." (PMID 39076470, 2024).
Atrophy (1 paper, 2021). Any weakening or degeneration, especially through lack of use. "Here we crossed Thbs1 DTG mice into the Atf6−/− genetic background, which did not reduce the atrophy associated with the Thbs1 DTG, nor did it extend viability." (PMID 34168130, 2021). "Deletion of Thbs1 effectors/receptors, including ATF6α, CD36 or CD47 does not diminish Thbs1-dependent cardiac atrophy." (PMID 34168130, 2021).
cartilage disease (1 paper, 2015). Softening and degeneration of the CARTILAGE. "The elucidation of ATF6’s role and molecular events involved in chondrocyte differentiation will better our understanding of normal cartilage development and the pathogenesis of cartilage disease." (PMID 26374329, 2015).
cerebral edema (1 paper, 2024). "The brain water content indicated that when the ATF6 protein level increased, the degree of cerebral edema decreased, indicating that ATF6 can alleviate cerebral edema caused by ICH." (PMID 38613810, 2024).